PKN3 (protein kinase N3)
Description:
Contributes to invasiveness in malignant prostate cancer.
Synonyms: PKNBETA; UTDP4-1
Tractability: Small molecule: a high-quality ligand is known; it belongs to a druggable protein family. PROTAC: it is named in the literature on targeted protein degradation; ubiquitination databases record sites on it; a small molecule that binds it is known.
Target class: AGC protein kinase PKN family; Enzyme; AGC protein kinase group; Protein Kinase; Kinase
Chemical probes: GSK902056A (high quality)
Gene: Protein-coding gene on chromosome 9 (128,702,499 to 128,720,924, forward strand). Ensembl gene ENSG00000160447.
Subcellular location: Nucleus; Cytoplasm, perinuclear region
Subcellular location (Human Protein Atlas): Vesicles
Pathways (Reactome):
Signal Transduction: RHO GTPases activate PKNs; RHOA GTPase cycle; RHOB GTPase cycle; RHOC GTPase cycle
Gene Ontology:
Molecular function: protein binding; protein kinase activity; protein serine/threonine kinase activity; ATP binding; diacylglycerol-dependent serine/threonine kinase activity; protein serine kinase activity; small GTPase binding
Biological process: epithelial cell migration; intracellular signal transduction; protein phosphorylation; signal transduction
Cellular component: cytosol; Golgi apparatus; nucleus; perinuclear region of cytoplasm
Genetic constraint (gnomAD): Loss-of-function variants: 88 observed, 106.49 expected, observed/expected ratio (o/e) 0.83, 90% interval 0.69 to 0.99. The upper end of that interval is the gene's LOEUF score, 0.99, which puts it in group 4 of 6, group 1 being the genes least tolerant of losing a copy. Missense variants: 989 observed, 1,147 expected, observed/expected ratio (o/e) 0.86, 90% interval 0.82 to 0.91. Synonymous variants: 442 observed, 471.06 expected, observed/expected ratio (o/e) 0.94, 90% interval 0.87 to 1.01.
Homologues: Orthologues: chimpanzee PKN3 (99% identical), macaque PKN3 (98% identical), dog PKN3 (89% identical), pig PKN3 (87% identical), guinea pig PKN3 (85% identical), rat Pkn3 (84% identical), mouse Pkn3 (83% identical), zebrafish pkn3 (54% identical), Drosophila melanogaster Pkn (48% identical), Caenorhabditis elegans pkn-1 (39% identical), Drosophila melanogaster Pkcdelta (30% identical), zebrafish prkcg (23% identical), and 4 more. Paralogues in human: PKN1 (52% identical), PKN2 (52% identical), PRKCE (24% identical), PRKCA (23% identical), PRKCH (23% identical), PRKCG (23% identical), PRKCB (23% identical), PRKCI (20% identical), PRKCZ (20% identical).
Diseases named in the same sentence as PKN3 in open-access papers:
PKN3 is named in the same sentence as 32 diseases in open-access papers, as found by Europe PMC text mining. Sharing a sentence is not in itself a finding about the gene and the disease. The quoted sentences say what the papers report.
prostate carcinoma (5 papers, 2014 to 2023). A carcinoma that arises from epithelial cells of the prostate gland. "In cancer cells, PKN3 was shown to act downstream of activated PI3K (phosphatidylinositol 3-kinase) promoting the malignant progression of prostate cancer." (PMID 33092266, 2020). "This analysis showed that elevated expression of PKN3 significantly positively correlates with the elevated expression of p130Cas and vice versa in both patients with breast cancer and those with prostate cancer." (PMID 30422386, 2019). "Moreover, downregulation of PKN3 expression led to impaired primary tumor growth and inhibition of metastasis in breast and prostate cancer." (PMID 33092266, 2020). "Previous studies showed positive correlation between PKN3 or p130Cas (BCAR1) protein levels and cancer progression in patients with breast or prostate cancer." (PMID 30422386, 2019). "This may have implications for interpreting the underlying mechanisms of action of Y27632 involving ROCK versus PKN3, for example, for inhibition of tumour metastasis in a PC3 prostate cancer xenograft model, a process in which PKN3 has been also implicated." (PMID 27919031, 2014).
pancreatic cancer (4 papers, 2019 to 2023). "An siRNA drug called Atu027 silenced the expression of a pro-metastatic ligand termed protein kinase N3 (PKN3) in endothelial cells and induced dramatic regression of distant metastasis of pancreatic cancer in phase I and II clinical trials." (PMID 37273004, 2023). "In addition to the KRAS mutation as therapeutic target for RNAi, other genes such as protein kinase N3 have been investigated as targets for siRNA in pancreatic cancer." (PMID 34683931, 2021). "As protein kinase N3 has previous been identified as a downstream effector of the PI3K signaling pathway, reduction of protein kinase N3 expression with Atu027 resulted in changes in tumor lymphatic vasculature, suggesting an anti-lymph angiogenesis therapeutic strategy for pancreatic cancer." (PMID 34683931, 2021). "Obtaining a successful knockdown of the target genes into mouse vascular endothelium, an Atu027 formulation was produced using AtuPLEX technology to load siRNA, targeting the Protein Kinase N3 (PKN3), which is implicated in metastatic pancreatic tumor cell growth." (PMID 31344836, 2019).
melanoma (3 papers, 2016 to 2022). A malignant, usually aggressive tumor composed of atypical, neoplastic melanocytes. "Taken together, these data demonstrated that stromal PKN3 plays important roles in metastasis of melanoma." (PMID 26742562, 2016). "Fibroblastic cells derived from PKN3 KO mice have lower cell migration activity, and PKN3 KO mice showed poor growth factor-induced angiogenesis and suppression of lung metastasis of B16 melanoma cells injected through tail vein." (PMID 26742562, 2016). "Stromal PKN3 has been demonstrated to promote metastasis formation of melanoma B16BL6 cells injected into mice, suggesting that cancer‐associated fibroblast could lead invasion of cancer cells in PKN3‐promoting manner." (PMID 30422386, 2019). "We demonstrated that genetic ablation of PKN3 inhibits angiogenesis ex vivo (aortic ring assay) and in vivo (corneal micropocket assay) and gives resistance to lung metastasis after tail vein injection of melanoma." (PMID 26742562, 2016). "Furthermore, the PKN3 KO mice exhibited an impaired lung metastasis of melanoma cells when administered from the tail vein." (PMID 26742562, 2016). "Thus, to clearly assess the role of host PKN3 in tumor metastasis, B16BL6 melanoma cells were injected into the tail vein of WT and PKN3 KO mice." (PMID 26742562, 2016). "Together with our data about VE-cadherin expression levels, the impairment of lung metastasis of melanoma in PKN3 KO mice may not be simply due to the stable elevation of the endothelial barrier in PKN3 KO mice." (PMID 26742562, 2016). "Notably, however, our immunoblotting and immunohistochemical analysis did not reveal the overexpression of VE-cadherin in PKN3 KO mouse lung tissues, even with clear metastatic foci of melanoma." (PMID 26742562, 2016).
breast carcinoma (2 papers, 2019 to 2020). "Here, we show a novel interaction of p130Cas with Ser/Thr kinase PKN3, which is implicated in prostate and breast cancer growth downstream of phosphoinositide 3‐kinase." (PMID 30422386, 2019). "The phosphoproteomic screen was performed in the lysate of MDA-MB-231 breast cancer cells expressing either PKN3 AS or PKN3 KD (kinase dead) as a control." (PMID 33092266, 2020). "Taken together, these results suggest that functional complex between PKN3 and p130Cas supports a more advanced malignant phenotype in breast cancer cells." (PMID 30422386, 2019). "To verify the involvement of p130Cas (BCAR1) in PKN3‐induced cancer progression, we performed a set of experiments with MDA‐MB‐231 breast cancer cells." (PMID 30422386, 2019). "This suggests that although PKN3 kinase is able to phosphorylate p130Cas on Ser432 (Ser428) in vitro and its activity correlates with this phosphorylation in breast carcinomas, PKN3 is not responsible for this phosphorylation in cells cultivated on plastic." (PMID 30422386, 2019).
Alzheimer disease (1 paper, 2020). A progressive, neurodegenerative disease characterized by loss of function and death of nerve cells in several areas of the brain leading to loss of cognitive function such as memory and language. "These loci were enriched in genes with functions related to Alzheimer's disease and cognitive decline, including GNB5, GNG7 and PKN3 (p < 0.05)." (PMID 32525932, 2020).
Arthritis (1 paper, 2016). Inflammation of a joint. "We speculate that PKN3 blocking strategies not only could be applied in cancer treatment, but also for other vascular diseases such as arthritis and age-related macular degeneration." (PMID 26742562, 2016).
atherosclerosis (1 paper, 2020). A disease characterized by the build-up of fatty material and calcium deposition in the arterial wall resulting in partial or complete occlusion of the arterial lumen. "Finally, PKN3 has been recently demonstrated to play a role in bone resorption downstream of non-canonical Wnt5a/ Ror2 signaling cascade that regulates the secretion of pro-inflammatory cytokines necessary for atherosclerosis development." (PMID 33092266, 2020). "Moreover, depletion of PKN3 was shown to attenuate pro-inflammatory activation of endothelial cells caused by defects in glycosylation of ICAM-1 adhesion molecules, suggesting its potential involvement in the promotion of atherosclerosis." (PMID 33092266, 2020).
bladder tumor (1 paper, 2019). "(2011) where only siRNA anti‐PKN1 or anti‐PKN2, but not anti‐PKN3, had an effect on wound healing closure of 5637 bladder tumor cells." (PMID 30422386, 2019).
breast tumour (1 paper, 2011). "The expression of PKN3 varied the most among tumour cell lines with for example very high and very low levels evident in breast tumour cell lines." (PMID 21754995, 2011).
cardiac hypertrophy (1 paper, 2023). "More specifically, PKN3 has been implicated in transcriptional regulation of the ANP gene that is associated with cardiac hypertrophy in response to phenylephrine." (PMID 37019881, 2023).
colon cancer (1 paper, 2014). "Another intriguing therapeutic strategy, which was clinically tested in patients with advanced colon cancer, targets Protein Kinase N3 (PKN3), an important mediator of the PI3K pathway." (PMID 26056574, 2014).
coronary artery disease (1 paper, 2020). "Interestingly, PKN3 was identified in a module of genes associated to transendothelial migration of leukocytes leading to coronary artery disease." (PMID 33092266, 2020).
dilated cardiomyopathy (1 paper, 2022). Cardiomyopathy which is characterized by dilation and contractile dysfunction of the left and right ventricles. "All PKN isoforms were detected in human hearts, but PKN2 expression increased in dilated cardiomyopathy (DCM) hearts relative to controls, whilst PKN1 and PKN3 declined." (PMID 35730579, 2022).
Gastrointestinal Neuroendocrine Tumor (1 paper, 2021). "Pkn3 contributes to disorders such as Pachyonychia Congenita 1, malignant prostate cancer, and Gastrointestinal Neuroendocrine Tumor." (PMID 34884814, 2021).
invasive breast carcinoma (1 paper, 2019). A carcinoma that infiltrates the breast parenchyma. "In parallel, we analyzed the available data on protein phosphorylation levels of PKN3 and p130Cas [Clinical Proteomic Tumor Analysis Consortium (CPTAC), MS analysis of 34 invasive breast carcinoma tumors]." (PMID 30422386, 2019).
leukemia (1 paper, 2020). A malignant (clonal) hematologic disorder, involving hematopoietic stem cells and characterized by the presence of primitive or atypical myeloid or lymphoid cells in the bone marrow and the blood. "The effect of PKN3 expression on regulation of cancer development was further highlighted in PKN3 knock-out mice that showed slower rates of leukemia development induced by the loss of PTEN (phosphatase and tensin homolog) and a decrease in the number of secondary tumor sites." (PMID 33092266, 2020).
Lewis lung carcinoma (1 paper, 2016). "To determine whether stromal PKN3 expression affects tumor growth and angiogenesis, we injected PKN3 KO and WT mice subcutaneously with 1 × 106 Lewis lung carcinoma cells and monitored tumor growth over time." (PMID 26742562, 2016).
pancreatic ductal adenocarcinoma (1 paper, 2021). An infiltrating adenocarcinoma that arises from the epithelial cells of the pancreas. "In 2014, Atu027, a lipid-based RNAi therapeutic aimed against the protein kinase N3 (PKN3) mRNA in the vascular endothelium to treat pancreatic ductal adenocarcinoma (PDAC), was well tolerated in a dose–escalation phase I clinical trial." (PMID 33921892, 2021).
tumor (16 papers, 2011 to 2026). "In particular, PKN3 has been implicated in tumor growth and metastatic progression, highlighting the need for isozyme-selective inhibitors as both research tools and therapeutic leads." (PMID 41752364, 2026). "In recent studies, PKN3 has been functionally linked to metastasis, invasion and tumor growth making it a potential target for drug discovery in oncolgy." (PMID 37904048, 2024). "Protein kinase N3 (PKN3) is a serine/threonine kinase implicated in tumor progression of multiple cancer types, however, its substrates and effector proteins still remain largely understudied." (PMID 33092266, 2020). "Elevated PKN3 expression is associated with enhanced angiogenesis and tumor metastasis; consequently, silencing PKN3 expression leads to the inhibition of angiogenesis and tumor invasion." (PMID 34371702, 2021). "One possible explanation would be that other PKN isoforms could compensate for the loss of PKN3 function in the context of tumor." (PMID 26742562, 2016). "Recently, PKN3 has also been considered as a suitable therapeutic target for modulating tumor angiogenesis because loss of function analysis with Atu027 in cultured primary endothelial cells showed an essential role of PKN3 for endothelial tube formation and migration." (PMID 24275949, 2013). "PKN3 physically interacts with Rho-family GTPases, and preferentially with RhoC, a known mediator of tumor invasion and metastasis." (PMID 40390497, 2025). "Atu027, a siRNA-based lipid nanoparticle designed to knock down protein kinase N3 (PKN3), is linked to angiogenesis and tumor metastasis." (PMID 40390497, 2025). "The knockdown of PKN3 in orthotopic mice demonstrated reduced tumor size and impaired tumor metastasis Atu027115, was tested in a Phase I trial involving 34 patients with advanced solid tumors." (PMID 40390497, 2025). "Atu027 is an RNA interference (RNAi) therapeutic specifically silencing PKN3 mRNA expression in the vascular endothelium, thereby potentially inhibiting the metastatic expansion of the tumor." (PMID 33114652, 2020). "Using orthotopic mouse tumor models, the effect of PKN3 on cancer growth was shown by conditional reduction of PKN3 expression in tumors." (PMID 30422386, 2019). "(2012) demonstrated that PKN3 physically interacts with Rho‐family GTPases, and preferentially with RhoC, a known mediator of tumor invasion and metastasis in epithelial cancers." (PMID 30422386, 2019). "Our data support these results and furthermore suggest that binding of PKN3 to p130Cas is important for PKN3‐induced tumor growth." (PMID 30422386, 2019). "The primary tumors were surgically removed at days 21 and 22 after inoculation for the SCpkn3−/− cell lines (+PKN3 WT, +mCherry, and +PKN3 mPR, respectively) and at day 16 in parental SC cells inducibly expressing mCherry owing to large tumor sizes." (PMID 30422386, 2019). "One of the confirmed partners, PKN3, has been reported to be involved in tumor angiogenesis and metastasis, and having a role as a downstream effector of PI3K signaling." (PMID 28569207, 2017). "This analysis was performed on a variety of adult mouse tissues and revealed ubiquitous expression, indicating that PKN3 mRNA is not limited to tumor cells." (PMID 26742562, 2016). "Here, we present in vivo genetic evidence that PKN3 in stromal cells play important roles in metastasis as evidenced by significantly smaller number and the smaller size of the metastatic tumor foci in the lungs of PKN3 KO mice than WT mice." (PMID 26742562, 2016). "Individual PKN isoforms vary in tissue distribution, with PKN1 and PKN2 ubiquitously expressed, and PKN3 mainly restricted to various tumour tissues." (PMID 27919031, 2014). "This drug is being investigated for its efficacy against solid tumors, because PKN3 knockdown may prevent metastasis by reducing vascular leakiness and tumor cell migration and tumor lymphangiogenesis and hemangiogenesis." (PMID 36735106, 2023).